ALK (ALK receptor tyrosine kinase)
Diseases named in the same sentence as ALK in open-access papers (continued):
Sharing a sentence is not in itself a finding about the gene and the disease.
gastric cancer (28 papers, 2013 to 2025). A primary or metastatic malignant neoplasm involving the stomach. "Given the rarity of both ALK mutation and the fusion type, here, we report a case of a gastric cancer patient with a driver mutation of DCTN1–ALK fusion." (PMID 41246301, 2025). "The KG data indicate that the ALK-p.L1196M mutation, which is associated with gastric cancer, has a known resistance to nalatinib." (PMID 39775838, 2025). "However, little was reported about ALK mutation in gastric cancer (GC)." (PMID 33692962, 2021). "Fortunately, ALKi, such as alectinib and lorlatinib, have demonstrated efficacy in inhibiting tumor growth and improving patient outcomes in ALK-mutant gastric cancer, offering a more effective and less toxic alternative to traditional chemotherapy." (PMID 41246301, 2025). "Anaplastic lymphoma kinase (ALK) rearrangements are exceedingly rare in gastric cancer, and uncommon fusion types add to the difficulties of proper, precise treatment strategies." (PMID 41246301, 2025). "Surprisingly, the three KIs share the same target, ALK and INSR, but only the ALK gene was found to have a high expression level in the gastric cancer cell line." (PMID 36145589, 2022). "Gene expression of AGP-01 cells and non-neoplastic gastric mucosa MNP-01 (normal cell) revealed that the ALK gene is overexpressed in the gastric cancer cells when compared to the normal cell line." (PMID 36145589, 2022). "Looking for another evidence that ALK can be a biomarker for gastric cancer, we identified a lower survival rate for patients with gastric cancer with high levels of ALK expression in TCGA-STAD analysis." (PMID 36145589, 2022). "Here we identified a novel form of ALK fusion, a case of GC with RAB10-ALK fusion, and this is the first report of ALK fusion in gastric cancer." (PMID 33692962, 2021). "A Korean gastric cancer cohort (n = 455) consisted of 38 ALK Immunohistochemistry (IHC)-positive (34 of 1+, and 4 of 2+/3+) patients who were younger and more likely to have signet ring cells, associated with worse disease-free survival (DFS) and overall survival (OS)." (PMID 41246301, 2025). "There is ample evidence that ALK overexpression may be a promising therapeutic biomarker for other populations in different continents, which could benefit gastric cancer patients." (PMID 36145589, 2022). "Therefore, our study corroborates with the possibility of the use of ALK target therapy against gastric cancer." (PMID 36145589, 2022). "Interestingly, the three molecules share the same targets, ALK and INSR, in which only the ALK gene is overexpressed in the gastric cancer cell line." (PMID 36145589, 2022). "To date, ALK alteration has been detected in only a few cases of gastric carcinoma." (PMID 35204520, 2022). "Drug screening studies in isogenic CDH1−/−-mutant mammary epithelial MCF10A and c.1380delA CDH1-mutant gastric cancer cells show considerable overlap in sensitivity to PI3K, mTOR, or ALK/ROS-1 like tyrosine kinase inhibition." (PMID 29468433, 2018). "For example, the MET and ALK tyrosine kinase inhibitor crizotinib (PF-02341066) shows differential antitumor effects in non-small cell lung and gastric cancer according to MET and ALK alterations." (PMID 26134786, 2015). "Tissue microarrays (TMAs) from consecutive gastric carcinoma (GC) and CRC patients who underwent surgical resection at Samsung Medical Center, Seoul, Korea were screened by IHC using ALK monoclonal antibody 5A4." (PMID 26172300, 2015).
gastric cancer (continued). "The gastric cancer case with ALK–HMBOX fusion failed to reveal the resistance mechanism by a second FoundationOne CDx test on the new cervical lymph node tissue specimen; however, the p.Val1180Leu ALKi resistance mutation was identified in ctDNA analyzed on a Illumina NextSeq 550 NGS instrument." (PMID 41246301, 2025). "Moreover, we performed the gene expression analysis of these targets on gastric cancer cells (AGP-01) and, interestingly, only the ALK gene showed a high expression level in gastric cancer cells when compared to the non-malignant cell line (sixfold changes)." (PMID 36145589, 2022). "Therefore, based on an actionable fusion frequency ≥0.5%, a clinically relevant response rate to ALK TKIs, and marginal additional cost when incorporated into existing comprehensive NGS workflows, we advocate routine ALK fusion assessment in all cases of metastatic or refractory gastric cancer." (PMID 41246301, 2025). "Given the rarity of reports regarding ALK and NUT alterations in gastric cancer, our results indicate that neither ALK nor NUT fusion plays a relevant role in gastric cancer." (PMID 35204520, 2022). "In summary, our results indicate that neither the expression of ALK, NUT, nor TRK plays a relevant role in gastric cancer." (PMID 35204520, 2022). "As is the case for ALK and NUT, NTRK fusions do not seem to be relevant in gastric cancer." (PMID 35204520, 2022). "ALK, NUT, and NTRK expression does not seem to play an important role in gastric carcinomas." (PMID 35204520, 2022).
mesenchymal tumors (28 papers, 2014 to 2026). "Epithelioid inflammatory myofibroblastic sarcoma (EIMS) is a rare and highly aggressive mesenchymal neoplasm that is frequently associated with anaplastic lymphoma kinase (ALK) gene fusion." (PMID 41777067, 2025). "Given the data to date, ALK expression may prove to be a valuable marker in helping distinguish EFH from related mesenchymal neoplasms in cases of diagnostic uncertainty." (PMID 28895885, 2017). "In one study, three of seven patients with ALK‐positive mesenchymal tumors responded to ALK inhibitors." (PMID 40904239, 2025). "Anaplastic lymphoma kinase (ALK) gene rearrangements have been increasingly detected in mesenchymal neoplasms." (PMID 40463972, 2025). "Herein, we firstly report a primary lung lesion presenting as a rare ALK-rearranged mesenchymal neoplasm." (PMID 40463972, 2025). "ALK-rearranged mesenchymal neoplasms occur mainly in superficial tissues but rarely in internal organs." (PMID 40463972, 2025). "ALK rearrangements occur in an emerging group of receptor tyrosine kinase (RTK) fusion-positive mesenchymal neoplasms." (PMID 40688914, 2025). "The patient diagnosed with primary pulmonary ALK-rearranged mesenchymal neoplasm (PPAMN) received ensartinib as postoperative adjuvant therapy, achieving a disease-free survival of 10 months." (PMID 40463972, 2025). "The largest study of ALK‐positive mesenchymal tumours (excluding myofibroblastic tumours) is a case series of seven ALK IHC positive tumours of which five harboured ALK gene rearrangements." (PMID 39188081, 2024). "Anaplastic lymphoma kinase (ALK) overexpression and gene alterations have been detected in several mesenchymal tumors, with significant implications for diagnosis, therapy and prognosis." (PMID 37120571, 2023). "The results indicated that PDGFRA-mutant GISTs should be considered a differential diagnosis when encountering an ALK-positive mesenchymal tumor, especially those with CD117-negative or weakly positive in immunohistochemical staining." (PMID 37120571, 2023). "The involvement of ALK in EFH pathogenesis was first documented with the report of two cases of cutaneous mesenchymal neoplasms found to stain for ALK by immunohistochemistry." (PMID 28895885, 2017). "In addition, this case also demonstrated that neoadjuvant therapy may be a better treatment strategy compared to upfront surgery for ALK-rearranged mesenchymal neoplasms with a relatively high tumor burden." (PMID 41672777, 2026). "This is the first case of ALK-rearranged mesenchymal neoplasm manifested as a primary lung lesion and a novel HMBOX1::ALK fusion was identified by NGS." (PMID 40463972, 2025). "Here, we reported ALK fusions involving related partner genes in two adult soft tissue tumors with S100 and CD34 co-expression, and conducted a literature review of mesenchymal tumors harboring ALK or other kinase fusions." (PMID 36387173, 2022). "More recently, ALK-rearranged mesenchymal tumors that are not IMTs or EFHs, characterized by S100 and CD34 coexpression, have been reported in a few small series and isolated case reports." (PMID 41672777, 2026). "In the present case, diagnosis was challenging due to the rapid enlargement of an ALK‐negative mesenchymal tumour." (PMID 41368177, 2025). "The family of ALK-rearranged mesenchymal neoplasms is expanding and ensartinib could be a potential treatment option for patients with HMBOX1::ALK." (PMID 40463972, 2025). "Alterations in the ALK gene are seen in several mesenchymal tumors, and since ALK is generally not expressed in normal fibroblasts, its activation and overexpression could play a significant role in the development of these tumors." (PMID 40951164, 2025). "Thus, we think it is difficult to rule out the possibility of ALK-rearranged mesenchymal tumors with the Cajal cell phenotype and positive expression of CD117 and DOG-1." (PMID 37120571, 2023).
mesenchymal tumors (continued). "Our study revealed 7.7% (4/52) of ALK expression in PDGFRA-mutant GISTs, indicating that molecular tests were required to rule out the possibility of PDGFRA-mutant GISTs when encountering ALK-positive mesenchymal tumors with CD117-negative or weakly positive in immunohistochemical staining." (PMID 37120571, 2023). "Anaplastic lymphoma kinase (ALK) overexpression was not expected to be present in the GIST, and it has been used as a biomarker to distinguish GISTs from other types of mesenchymal tumors." (PMID 32005261, 2020). "In summary, we described four extra-abdominal round cell/epithelioid mesenchymal neoplasms sharing EWSR1::ATF1 fusions, frequent expression of epithelial and neuroendocrine markers, occasional aberrant expression of ALK and MUC4, but not fitting with any currently defined mesenchymal neoplasm." (PMID 39031200, 2024).
colon carcinoma (23 papers, 2014 to 2025). "These 53 ALK variants were identified in 77 patients (40 males, 37 females), with the highest frequency in corpus uteri (15.58%), followed by adrenal gland (11.69%), skin (10.39%), lung (9.09%), and colon cancer (9.09%)." (PMID 40606598, 2025). "After 12 cycles of cetuximab/FOLFIRI (5-fluorouracil, leucovorin, irinotecan) chemotherapy, the patient underwent palliative surgical resection of colon cancer which revealed poorly differentiated adenocarcinoma, demonstrated diffuse and intense ALK staining (3+) by ALK IHC." (PMID 26172300, 2015). "In addition, METex14del occurs exclusively to ALK, ROS1, NTRK1, NTRK3 or RET fusions indicating METex14del is likely a driver mutation and defines a unique molecular subset of gastric and colon cancers." (PMID 26375439, 2015). "To experimentally examine the patient data-driven hypothesis of ALK pathway involvement in CMS1 colon cancer subtype, we treated CMS1 (LoVo and SW48), CMS2 (LS1034 and NCIH508), CMS3 (HT29 and LS174T) and CMS4 (HCT116 and Caco-2) cell lines with increasing concentrations of CZB or ALC." (PMID 35351152, 2022). "Simultaneous activation of the two WNT pathways has been reported in colon cancer cells, and the WNT/β-catenin pathway is upregulated in a highly tumorigenic subpopulation of ALK+ ALCL cell lines." (PMID 35246138, 2022). "The cancer-reducing effect of ALK TKI on CMS1 was demonstrated in a 3D spheroid model and in a physiologic mouse model, supporting the potential for a clinical trial using combination therapy containing ALK TKI to treat the CMS1 subtype of colon cancer." (PMID 37892172, 2023). "Interestingly, Crizotinib induces proliferation in cell lines exhibiting CMS-4, suggesting that ALK TKI is not universally beneficial for colon cancer patients." (PMID 37892172, 2023).
multiple myeloma (23 papers, 2009 to 2025). "The differentials include plasma cell myeloma, ALK-positive large B-cell lymphoma, HHV-8-associated large B-cell lymphoma, and primary effusion lymphoma." (PMID 39944461, 2025). "His brain MRI and PET/CT are negative for recurrence, demonstrating a durable response to targeted ALK inhibition surpassing conventional systemic myeloma therapy including autologous stem cell transplantation." (PMID 33731690, 2021). "It would be of interest to try agents borrowed from plasma cell myeloma regimens or agents active in novel pathways in combination with chemotherapy given ALK-DLBCL plasmacytic nature." (PMID 19250532, 2009). "An ALK inhibitor combined with a myeloma-like regimen is effective in these patients." (PMID 39906668, 2024). "There are reports of encouraging efficacy of a myeloma-like regimen in patients with ALK+ LBCL." (PMID 39906668, 2024). "The differential diagnosis includes immunoblastic DLBCL and other lymphoid neoplasms with plasmacytic features such as ALK-positive DLBCL, primary effusion lymphoma (PEL), BL with plasmacytoid differentiation and plasmablastic plasmacytoma/myeloma." (PMID 26108914, 2015). "LTK is a paralog of anaplastic lymphoma kinase ALK, and is only expressed in myeloma cells following the rare event of an ALK-translocation; hence, ALK-inhibitors have not generally been used in myeloma therapies." (PMID 40634511, 2025). "Taken together we confirm that myeloma cells express LTK, but not ALK, and that the main isoform of LTK in myeloma cells localizes to the ER and can be inhibited by ALK inhibitors." (PMID 40634511, 2025). "We found that the majority of patients (83%) had myeloma cells expressing LTK, but not ALK (0.1%)." (PMID 40634511, 2025).
papillary thyroid cancer (21 papers, 2014 to 2026). "A study of the translocation profile of ALK in DTC found ALK translocations in 11 of 498 papillary thyroid cancers (PTCs) (2.2%) and 3 of 23 diffuse sclerosing variant PTCs (13%)." (PMID 31533238, 2019). "Mutations in the BRAF-V600E gene occur in approximately 45% of papillary thyroid cancers, while mutations in the RAS and ALK genes are frequently found These mutations drive mTOR pathway activation and lead to thyroid tumourigenesis." (PMID 37773165, 2023). "TRK rearrangements are found in only 1–5% of papillary thyroid carcinomas, and at higher frequencies in patients with a history of radiation exposure, the anaplastic lymphoma kinase gene (ALK) was found in 1% of papillary thyroid cancers." (PMID 36980552, 2023). "We describe a case of a 30-year-old man with a locally aggressive form of papillary thyroid cancer with EML4e13-ALKe20 fusion (EML4: echinoderm microtubule-associated protein-like 4; ALK: anaplastic lymphoma kinase)." (PMID 33628533, 2021). "Anaplastic lymphoma kinase (ALK) gene fusions are rare in papillary thyroid carcinoma (PTC) but may serve as a therapeutic target." (PMID 38642308, 2024). "The other molecular alterations that are less frequent in papillary thyroid carcinomas are E1F1AX, ALK fusion, NTRK1, or NTRK3 fusion." (PMID 36980552, 2023). "In order to assess the prevalence of ALK-rearrangements, and particularly the STRN/ALK fusion occurrence in thyroid tumors more precisely, a larger batch of papillary thyroid carcinomas and anaplastic thyroid carcinomas will be screened via FISH and RT-PCR in the near future." (PMID 24475247, 2014).
adenosquamous carcinoma (20 papers, 2013 to 2024). A carcinoma composed of malignant glandular cells and malignant squamous cells. "The aim of our study was to assess EGFR-mutations and ALK-rearrangements in different intratumor subtypes and/or growth patterns in a series of mixed adenocarcinomas and adenosquamous carcinomas." (PMID 26422230, 2015). "Another patient (case #18) presented initially with moderately differentiated adenosquamous carcinoma in the first biopsy specimen collected in his right lung lesion, which was ALK positive by FISH." (PMID 32674491, 2020). "Three of these cases with the ALK fusion gene (+) are adenosquamous carcinoma, and the remaining 17 cases are adenocarcinoma." (PMID 29587818, 2018). "On the contrary, ALK-rearrangement showed an intratumor heterogeneity in both mixed adenocarcinomas and adenosquamous carcinomas." (PMID 26422230, 2015). "This might explain the previously unappreciated role of ALK fusion in adenosquamous carcinoma development, since most mouse models were based on the origin of a type II pneumocyte." (PMID 37051524, 2023). "Fourteen cases (2.7%) harbored ALK fusion, including eight solid adenocarcinomas with signet ring cell features, four acinar adenocarcinomas with cribriform pattern containing mucin, one adenosquamous carcinoma and one micropapillary adenocarcinoma with mucin." (PMID 34234236, 2021). "FISH analysis confirmed the presence of ALK gene rearrangement in only sevenpatients (4.8% of all patients, 20.7% of RT-PCR positive patients) including six patients with adenocarcinoma (7.5%; 6/80) and single patient with adenosquamous carcinoma." (PMID 28534101, 2017). "If p63 was used as a squamous cell marker to make a pathological diagnosis, ALK-rearranged tumors could be misdiagnosed as adenosquamous cell carcinomas." (PMID 23922677, 2013). "The patient underwent salvage pulmonary resection, and the pathology revealed adenosquamous carcinoma and wild-type for EGFR and ALK." (PMID 36434641, 2022). "ALK gene rearrangement was not confirmed in male patient with adenosquamous carcinoma, with abnormal ALK protein expression on only 5% of tumor cells." (PMID 28969070, 2017). "While our manuscript was under review, a paper appeared showing an intratumor heterogeneity of ALK rearrangement in a total of 7 NSCLC tumor samples (seven out of ten ALK positive tumors detected in a series of 105 mixed adenocarcinomas and 17 adenosquamous carcinomas)." (PMID 26968843, 2016). "Interestingly, ALK gene rearrangement was revealed by both IHC and FISH in 5 of our 8 MEC-like cases, including 4 adenocarcinomas and 1 adenosquamous carcinoma." (PMID 26575266, 2015). "Although its sensitivity to ALK inhibitors is unknown, the fact that this was a case of adenosquamous carcinoma but not pure adenocarcinoma may be one reason for its aggressive nature." (PMID 31030664, 2019).
gastrointestinal stromal tumor (20 papers, 2014 to 2026). "Existing literature reports that the smooth muscle differentiation of gastrointestinal stromal tumor (GIST) cells is associated with EML4::ALK." (PMID 39867882, 2024). "HSP90 inhibitors are currently being developed in ALK-translocated lung cancer, myeloma and gastrointestinal stromal tumor (GIST)." (PMID 25285786, 2014). "However, there are very few reports regarding the aberrant expression of ALK in gastrointestinal stromal tumors (GISTs)." (PMID 37120571, 2023). "However, few studies have investigated the correlation between ALK expression status and clinicopathological characteristics in patients with gastrointestinal stromal tumors (GISTs)." (PMID 37120571, 2023). "While no other malignancy fits this model quite as well as CML, there are similar resistance mutation phenomena in Gastrointestinal stromal tumour (GIST), Ph + acute lymphoblastic leukaemia (ALL), EGFR-mutant non small cell lung cancer (NSCLC), ALK-rearranged NSCLC, and other cancers." (PMID 31138173, 2019). "Tier IB predictors were identified in NB (ALK aberrations, 31 patients) and gastrointestinal stromal tumor (GIST, KIT amplification, one patient)." (PMID 41373618, 2025). "AT13387 is now undergoing clinical trials in phase I and II including patients with prostate carcinomas, refractory gastrointestinal stromal tumors (GIST) and ALK positive lung cancer." (PMID 26452257, 2015). "Gastrointestinal stromal tumors (GISTs): exhibit positive immunohistochemical staining for CD117, DOG-1, CD34, and C-KIT, but are negative for ALK." (PMID 39703852, 2024).